SEMA4D (semaphorin 4D)
Diseases named in the same sentence as SEMA4D in open-access papers (continued):
Sharing a sentence is not in itself a finding about the gene and the disease.
myeloma (5 papers, 2018 to 2022). "In a clinical study, serum levels of SEMA4D positively correlated with serum markers of resorption in patients with multiple myeloma." (PMID 35775083, 2022). "Sema4D seems not to be produced directly by the myeloma cells, as only one myeloma cell line produced high levels of Sema4D." (PMID 29748532, 2018). "Our data suggest that Sema4D is elevated in MM patients and correlate with adverse myeloma features and increased bone resorption, providing a possible target for novel therapeutic approaches in MM." (PMID 29748532, 2018). "We have shown that myeloma cell lines and primary myeloma cells express Sema4D at higher levels than MDA-MB-131 cells." (PMID 29971044, 2018). "Sema4D is, therefore, a potential target in myeloma, as well as in cancers that metastasize to the skeleton." (PMID 29971044, 2018). "On the other hand, the strong correlation of Sema4D with bone resorption marker CTX suggests that Sema4D contributes to bone destruction in myeloma." (PMID 29748532, 2018). "Terpos and coworkers showed increased Sema4D in peripheral blood and bone marrow plasma from myeloma patients compared to controls." (PMID 29971044, 2018). "Moreover, myeloma cell-conditioned medium induced SEMA4D expression in osteoclasts, featuring an additional paracrine mechanism to inhibit osteoblasts activity." (PMID 31143707, 2019). "Thus, SEMA4D signaling in myeloma cells seems to act both directly and indirectly to hinder bone formation." (PMID 31143707, 2019). "It was then mechanistically investigated the relevance of SEMA4D in myeloma cells by knock down experiments; notably, SEMA4D expression was found to mediate paracrine signaling preventing the induction of the pivotal differentiation factor Runx2 in osteoprogenitor cells." (PMID 31143707, 2019). "In addition, we found that coculture of myeloma cells with bone increased expression of Sema4D by both tumor cells and bone." (PMID 29971044, 2018). "Furthermore, its correlation with ISS and diffuse MRI pattern strongly suggest that high Sema4D is produced when myeloma load is also high." (PMID 29748532, 2018). "Our preliminary data also support the potential of Sema4D blockade in multiple myeloma." (PMID 29971044, 2018). "Thus, we evaluated Sema4D and Plexin-B1 in six myeloma cells lines in vitro; in the bone marrow plasma (BMP) and serum of 72 newly diagnosed symptomatic MM (NDMM) patients and in 25 healthy controls." (PMID 29748532, 2018). "Furthermore, the strong association between Sema4D and ISS staging and diffuse MRI pattern of marrow infiltration, which were observed in this study, suggests a correlation of Sema4D with myeloma burden." (PMID 29748532, 2018). "Sema4D can promote angiogenesis, which is required for myeloma progression." (PMID 29971044, 2018).
postmenopausal osteoporosis (5 papers, 2020 to 2024). Metabolic disorder associated with fractures of the femoral neck, vertebrae, and distal forearm. "The injection of a blocking antibody against Semaphorin 4D prevented bone loss due to ovariectomy in a postmenopausal mouse model, suggesting that the Semaphorin 4D–Plexin-B1 interaction is important for the pathogenesis of postmenopausal osteoporosis." (PMID 38731934, 2024). "It has been previously shown that the administration of an anti-Sema4D antibody inhibits neuroinflammation during EAE development and is protective against bone loss in a mouse model of postmenopausal osteoporosis." (PMID 35850304, 2022).
acute myeloid leukemia (4 papers, 2022 to 2024). Acute myeloid leukemia (AML) is a group of neoplasms arising from precursor cells committed to the myeloid cell-line differentiation. "Our findings indicate that SEMA4D expression is upregulated in human acute myeloid leukemia and corresponds with prognosis and risk stratification." (PMID 35794581, 2022). "AML cells were transfected with lentiviral over-expressing SEMA4D and si-PlexinB1 to further verify the effects of SEMA4D and the receptor PlexinB1 on cells in acute myeloid leukemia." (PMID 35794581, 2022). "We speculate that SEMA4D may also affect the proliferation and survival of cells by affecting the PI3K/Akt pathway in acute myeloid leukemia." (PMID 35794581, 2022).
Alzheimer disease (4 papers, 2021 to 2025). A progressive, neurodegenerative disease characterized by loss of function and death of nerve cells in several areas of the brain leading to loss of cognitive function such as memory and language. "Semaphorin 4D (SEMA4D) expression in the context of disease-associated neuropathology was assessed in postmortem brain sections of patients with Huntington’s (HD) and Alzheimer’s disease (AD), as well as in mouse models of HD (zQ175) and AD (CVN; APPSwDI/NOS2−/−) by immunohistochemistry." (PMID 35933420, 2022).
Arthritis (4 papers, 2015 to 2025). Inflammation of a joint. "Reductions were evident for mRNA for SEMA4D, which has altered expression in arthritis, and ITPKB, encoding an inositol phosphate kinase involved in stem cell division." (PMID 26544975, 2015). "Moreover, Sema4D induces the production of inflammatory mediators by RA monocytes, while the administration of an anti-Sema4D antibody reduces the arthritis severity and inflammatory cytokines in the Collagen Induced Arthritis (CIA) mouse model." (PMID 40598553, 2025). "Notably, soluble Sema4D levels have been found to be elevated in the serum and synovial fluid of patients with RA, and the administration of anti-Sema4D ameliorated inflammation in type II collagen-induced arthritis in mice." (PMID 30538782, 2018).
asthma (4 papers, 2018 to 2024). "Studies have shown that Sema4D can directly increase TGF-β1; IL-13 and TGF-β1 were decreased in a Sema4D−/− mouse model of experimental asthma." (PMID 32944173, 2020). "Sema4D can directly increase TGF-β1 expression, and IL-13 and TGF-β1 expression was decreased in a Sema4D −/− mouse model of experimental asthma." (PMID 32944173, 2020).
B cell lymphoma (4 papers, 2008 to 2026). "However, SEMA4D is rare in B-cell non-Hodgkin's lymphomas, suggesting that its loss might lead to decreased cell adhesion, increased mobility and metastatic potential." (PMID 18781179, 2008). "T cell lymphomas universally express Sema4D, while only a minority of B cell lymphomas are Sema4D positive, paralleling the expression of Sema4D by normal T and B cells." (PMID 29971044, 2018).
cervical cancer (4 papers, 2016 to 2023). A primary or metastatic malignant neoplasm involving the cervix. "In addition, analysis of survival data provided compelling evidence that high levels of Sema4D were significantly associated with an unfavorable outcome in cervical cancer patients." (PMID 33537086, 2021). "PlexinB1 inhibition experiments demonstrated that its ligand Sema4D enhances cervical cancer cell invasive potential." (PMID 33537086, 2021). "For example, COS7 cells and cervical cancer cell lines express plexin-B1 and its ligand Sema4D, and thus Sema4D is likely to act in an autocrine manner to stimulate plexin-B1." (PMID 27656111, 2016). "Moreover, Sema4D plays an important role in cervical cancer, due to its involvement in lymphangiogenesis and tumor cell migration." (PMID 33537086, 2021).
diabetes (4 papers, 2013 to 2022). "Sema4d−/− mice show attenuated pathological retinal neovascularization and vascular leakage in a streptozotocin-induced diabetes or oxygen-induced retinopathy model, indicating the pathological roles of Sema4D signaling in retinopathy." (PMID 35045890, 2022). "In mice, streptozotocin-induced diabetes or oxygen-induced retinopathy induces Sema4D expression in the retina." (PMID 35045890, 2022). "In summary, we report here that soluble Sema4D is present in the plasma of healthy individuals and that the level was increased in HF patients, especially in those with concurrent diabetes." (PMID 23741311, 2013). "Indeed, IRF1 was increased in retinas during OIR and STZ‐induced diabetes, which paralleled the expression pattern change of Sema4D." (PMID 31943789, 2020). "Furthermore, one single anti‐Sema4D (IVI) injection in the STZ model at 5 months after diabetes onset also reduced vascular leakage as shown at 1 week postinjection." (PMID 31943789, 2020). "Furthermore, Sema4D KO alleviated diabetes mellitus‐induced acellular capillary formation (and EV1A and B)." (PMID 31943789, 2020). "Therefore, our investigation shows that plasma Sema4D levels are increased in HF patients, especially in those who also have diabetes." (PMID 23741311, 2013). "Conversely, HF and diabetes may result in high levels of plasma Sema4D, which in turn may exacerbate HF and diabetes." (PMID 23741311, 2013). "In HF patients, plasma Sema4D levels were significantly higher than those in healthy controls (8.94±5.89 ng/mL, n = 157 vs. 4.67±2.99 ng/mL, n = 126, P<0.0001) with the highest levels being in HF patients with diabetes mellitus (DM) (10.45±5.76 ng/mL, n = 40)." (PMID 23741311, 2013). "Normal-Exos and miR-140-3p overexpressed-Exos accelerated diabetic wound healing by promoting the osteoblastogenesis function of BMSCs through inhibition plexin B1 expression which is the receptor of Sema4D and the plexin B1/RhoA/ROCK pathway compared with diabetes mellitus-Exos." (PMID 35236339, 2022). "To evaluate whether Sema4D KO inhibits the process of DR in an STZ model, we induced diabetes in Sema4D‐KO mice and age‐matched WT mice." (PMID 31943789, 2020). "Another notable finding of this study is that plasma Sema4D levels in HF patients with diabetes were even higher than those in HF patients without diabetes." (PMID 23741311, 2013). "HF patients with diabetes (10.45±5.76 ng/mL, n = 40) or without diabetes (8.42±5.87 ng/mL, n = 117) had higher plasma Sema4D levels than healthy controls (4.67±2.99 ng/mL, n = 126) (both P values <0.01)." (PMID 23741311, 2013).
diabetic retinopathy (4 papers, 2020 to 2022). "Sema4d not only acts as a biomarker but also plays a significant role in progression of diabetic retinopathy." (PMID 34319011, 2021). "The anti-Sema4D antibody has a synergistic therapeutic effect with the anti-VEGF antibody to improve the treatment of diabetic retinopathy." (PMID 32781674, 2020).
gastric cancer (4 papers, 2021 to 2025). A primary or metastatic malignant neoplasm involving the stomach. "It has been shown that TAM-derived Sema4d promotes angiogenesis, invasion, and metastasis in breast and gastric cancer." (PMID 39425000, 2025). "Moreover, the combined detection of CD68 and Sema4D protein markers was shown to have a potential for predicting gastric carcinoma progression and prospective patient prognosis." (PMID 33537086, 2021).
lymph node metastasis (4 papers, 2016 to 2021). "In the univariate analysis, histology, the depth of tumor invasion, lymph node metastasis, lymphatic invasion, venous invasion and positivity for both Sema4D and PlexinB1 were found to be significantly associated with overall survival." (PMID 27456345, 2016). "In the univariate analysis, histology, the depth of tumor invasion, lymph node metastasis, lymphatic invasion, venous invasion and positivity for both Sema4D and PlexinB1 were found to be significantly associated with RFS." (PMID 27456345, 2016). "Similarly, in non-small cell lung carcinomas, Sema4D expression serves as an early predictor of a poor prognosis as its overexpression is associated with a poor pTNM (Classification of Malignant Tumours) staging and occurrence of lymph node metastasis." (PMID 30134791, 2018). "The expression of Sema4D was significantly related to stage, the depth of tumor invasion, lymph node metastasis, lymphatic invasion, and venous invasion." (PMID 27456345, 2016). "The results indicated the shorter median PFS and OS were associated with low histologic grade, advanced stage, lymph node metastasis, residual disease ≥1 cm, VEGF positive expression, SEMA4D positive expression, PD-L1 positive expression, and patients' response to BC (all of them P < 0.05)." (PMID 31105696, 2019). "The increased Sema4D expression in these patients was associated with increased VEGF-C/VEGF-D levels, the presence of lymphatic invasion, the occurrence of lymph node metastasis, the International Federation of Gynecology and Obstetrics (FIGO) disease stage, and poor survival prognosis." (PMID 30134791, 2018). "However, a multivariate analysis demonstrated that lymph node metastasis (HR 2.783, CI 1.425–5.822; P = 0.002), and the positive expression of both Sema4D and PlexinB1 (HR 1.079, CI 1.013–2.868; P = 0.044) were an independent risk factors for worse survival." (PMID 27456345, 2016).
soft tissue sarcoma (4 papers, 2010 to 2021). A malignant neoplasm arising from muscle tissue, adipose tissue, blood vessels, fibrous tissue, or other supportive tissues excluding the bones. "Sema4D is indeed highly expressed in a wide range of human tumors such as prostate, colon, breast, oral, head and neck carcinomas as well as soft tissue sarcomas." (PMID 20858260, 2010). "SEMA4D has the capacity of inducing B-cells to aggregate and improves their viability,and high expression levels of SEMA4D are significantly correlated with poor prognosis for a number of cancers including colon, ovarian epithelial and cervical as well as soft tissue sarcoma." (PMID 34659201, 2021). "A recent clinical study on soft tissue sarcomas revealed that higher Sema4D expression was correlated with higher mitotic counts, cellularity, a higher necrosis ratio and Ki-67 index, suggesting a proliferative advantage in tumors with higher Sema4D expression." (PMID 20858260, 2010).
acute lymphoblastic leukemia (3 papers, 2022 to 2026). Leukemia with an acute onset, characterized by the presence of lymphoblasts in the bone marrow and the peripheral blood. "SEMA4D has been shown to be highly expressed in childhood acute lymphoblastic leukemia and promotes ALL development by activating PI3K/Akt and ERK signaling pathways." (PMID 35794581, 2022). "Semaphorin 4D (Sema4D)/(CD100) expression is upregulated in different human cancers, and it is associated with poor prognosis; however, its prognostic value in B-acute lymphoblastic leukemia (B-ALL) remains unclear." (PMID 41998221, 2026).
cholangiocarcinoma (3 papers, 2021 to 2023). A carcinoma that arises from the intrahepatic biliary tree (intrahepatic cholangiocarcinoma) or from the junction, or adjacent to the junction, of the right and left hepatic ducts (hilar cholangiocarcinoma). "A number of highly mutated cell signaling pathways are new to cholangiocarcinoma and possess immune-based functions including ADP-ribosylation factor 6 (ARF6) trafficking (FDR 0.047), Semaphorin 4D (SEMA4D) (FDR 0.047) and Rho-Roc signaling (FDR 0.049)." (PMID 37095160, 2023). "Regulation of SEMA4D in the cholangiocarcinoma can be affected by sponging miR-612 via lncRNA LINC01061." (PMID 35581633, 2022). "Consistently, KIKAT/LINC01061 has recently been reported to regulate the oncogenic role of SEMA4D in cholangiocarcinoma." (PMID 34111227, 2021).
Chronic Lymphocytic Leukemia (3 papers, 2019 to 2022). "SEMA4D/CD100 was found to be expressed in B-cell chronic lymphocytic leukemia (CLL) cells and in normal CD5+ B lymphocytes, and its high-affinity receptor Plexin-B1 was found in BM stromal cells, follicular dendritic cells, and activated T lymphocytes." (PMID 31143707, 2019). "In chronic lymphocytic leukemia, Sema4D promotes proliferation and inhibits apoptosis, but the roles of Sema4D in acute leukemia are not fully clarified." (PMID 35401878, 2022).
COVID-19 (3 papers, 2022 to 2024). A disease caused by infection with severe acute respiratory syndrome coronavirus 2. "Independent investigations have also found that genes related with some of these transcripts (IGI27, SEMA4D, SIGLEC1, and SERPINA1) are repressed in severe COVID-19, underlining their potential as early predictors of severity." (PMID 37918965, 2024). "Concentrations of the serum semaphorins SEMA3A, SEMA3C, SEMA3F, SEMA4D and SEMA7A were detectable in all patients with COVID-19." (PMID 37893159, 2023).
dyslipidemia (3 papers, 2013 to 2023). "They found that the loss of Sema4D expression ameliorates the effects of dyslipidemia on the platelet function in vivo and ex vivo, and reduces atherosclerotic lesions in hyperlipidemic mice on a high-fat, high-cholesterol diet for 3 or 6 months." (PMID 30405423, 2018). "Sema4D knockout inhibits collagen-induced platelet accumulation and contact in vitro, and it leads to decreased platelet accumulation in the acutely injured endothelium in mice with normal lipid levels and those with dyslipidemia." (PMID 37398659, 2023). "Moreover, the function of Sema4D in dyslipidemia-induced atherosclerosis has been described." (PMID 37398659, 2023).
epilepsy (3 papers, 2021 to 2024). A brain disorder characterized by episodes of abnormally increased neuronal discharge resulting in transient episodes of sensory or motor neurological dysfunction, or psychic dysfunction. "Finally, we report an epilepsy-associated de novo mutation in Sema4D (Q497P) that inhibits normal glycosylation and plasma membrane localization of Sema4D-associated complexes." (PMID 39152101, 2024). "SEMA4D also promotes inhibitory synapse formation and alleviates seizures in an animal model of epilepsy." (PMID 34301297, 2021). "A direct effect of mutation at 497 may be interference with the previously reported function of Sema4D in receptor clustering during GABAergic synapse development, thereby leading to imbalances in connectivity and epilepsy." (PMID 39152101, 2024).
Obesity (3 papers, 2020 to 2024). Accumulation of substantial excess body fat. "Bone turnover markers, sclerostin, periostin and semaphorin 4D were assessed before and 1, 12 and 24 months after SG, and aBMD was determined by DXA at baseline and after 12 and 24 months in 83 patients with obesity." (PMID 37892386, 2023).
pancreatic neuroendocrine cancer (3 papers, 2021 to 2022). "According to Zuazo-Gaztelu and colleagues, SEMA4D expression increased with tumor progression in pancreatic neuroendocrine cancer, and anti-SEMA4D antibody reduces tumor growth and tends to lengthen mouse lifespan." (PMID 35794581, 2022). "Targeting SEMA4D had been ongoing at early-stage clinical trials, such as in neuroendocrine pancreatic cancer." (PMID 33957921, 2021).
Sepsis (3 papers, 2023 to 2025). Sepsis is defined as life-threatening organ dysfunction caused by a dysregulated host response to infection. "In our sepsis cohort, SEMA kinetics were linked to sepsis complications with SEMA3A, SEMA3C, SEMA4D and SEMA7A associated with mortality." (PMID 40869413, 2025). "In conclusion, we have shown that patients with sepsis have different serum concentrations of SEMA3A, SEMA3C, SEMA3F, SEMA4D, and SEMA7A compared to healthy controls and that their kinetics during sepsis correlate with disease severity and outcomes." (PMID 39770766, 2024). "Patients with sepsis had significantly higher serum levels of SEMA3C, SEMA3F, SEMA4D, and SEMA7A and a significantly lower SEMA3A." (PMID 39770766, 2024). "While SEMA3A was decreased, SEMA3C, SEMA3F, SEMA4D, and SEMA7A were increased in sepsis patients, and all analyzed SEMA showed good accuracy in identifying patients with sepsis." (PMID 39770766, 2024). "Furthermore, the kinetics of SEMA were related to sepsis complications; SEMA3A, SEMA3C, SEMA3F, and SEMA4D were related to respiratory failure; SEMA3C and SEMA7A were related to acute kidney injury, while SEMA3C and SEMA3F were related to septic shock." (PMID 39770766, 2024). "While SEMA3A was decreased, SEMA3C, SEMA3F, SEMA4D, and SEMA7A were increased in sepsis patients." (PMID 39770766, 2024).